NEAT1 (nuclear paraspeckle assembly transcript 1)
Diseases named in the same sentence as NEAT1 in open-access papers (continued):
Sharing a sentence is not in itself a finding about the gene and the disease.
cancer (479 papers, 2013 to 2026). A tumor composed of atypical neoplastic, often pleomorphic cells that invade other tissues. "NEAT1’s promoter region mutations have been linked to the development of cancer in normal breast and renal cells." (PMID 41244835, 2025). "Over a thousand human genes have pUGs longer than 24 repeats, including the cancer-associated lncRNA NEAT1." (PMID 40682817, 2025). "Lately, association studies using targeted gene approaches have unveiled a connection between single-nucleotide polymorphisms (SNPs) of NEAT1 gene and distinct types of cancers." (PMID 41323778, 2025). "As NEAT1 is strongly implicated in the progression of various cancers, its underlying molecular mechanisms have been extensively investigated." (PMID 40521240, 2025). "Neat1 is linked to several human cancers, including thyroid, pancreatic, hepatic, and breast cancers 16-19." (PMID 40027195, 2025). "NEAT1 is associated with RBPs like HNRNPK (heterogeneous nuclear ribonucleoprotein K) in various cancers including HNSCC and promotes tumor growth." (PMID 40231344, 2025). "Dysregulation of NEAT1 has been found in almost all cancers and is associated with chemotherapy resistance and poor prognosis." (PMID 40682817, 2025). "Among the highly expressed lncRNAs are GAS5 (also known as SNHG2), SNHG1, NORAD, and NEAT1, abundant transcripts implicated in cell-cycle control, cancer progression, DDR, and inflammation, respectively." (PMID 41369348, 2025). "Higher levels of NEAT1 are known to indicate poor survival in cancer patients, are associated with progression and bone metastasis in PCa patients, and reduce sensitivity to chemotherapy." (PMID 41303378, 2025). "Numerous studies have reported that NEAT1 expression is associated with chemotherapy resistance in various cancer cells and isolated exosomes." (PMID 39401197, 2024). "The expression of NEAT1 has demonstrated a significant association with unfavorable survival outcomes across a range of cancers." (PMID 38343745, 2024). "NEAT1 is also abnormally expressed in many cancers and associated with therapy resistance and poor clinical outcomes." (PMID 38611028, 2024). "The findings have consistently unveiled that the depletion of NEAT1 can enhance the susceptibility of cancer cells to radiation or pharmacological agents by disrupting NEAT1-mediated ceRNA networks." (PMID 38343745, 2024). "NEAT1 is widely overexpressed in human cancers and is associated with poor clinical outcomes, which have been attributed in part to an essential role for forming paraspeckles in the response to loss of homeostasis." (PMID 38802648, 2024). "For instance, metastasis-associated lung adenocarcinoma transcript 1 (MALAT1) and nuclear-enriched abundant transcript 1 (NEAT1) are strongly implicated in cancer progression and metastasis in various cancer types." (PMID 39199690, 2024). "NEAT1 is dysregulated in a wide range of cancers and is significantly associated with complex clinicopathological features." (PMID 38970092, 2024). "NEAT1 is implicated in promoting cancer cell proliferation and autophagy through a competing endogenous RNA (ceRNA) mechanism, highlighting its functional importance in the cytoplasm as well." (PMID 39715205, 2024). "Long non-coding RNA nuclear paraspeckle assembly transcript 1 (LncRNA NEAT1) has been shown to be closely associated with chemotherapy resistance in cancer." (PMID 38970092, 2024). "NEAT1 knockdown is implicated in cancer cell sensitization to chemotherapy, and attenuation of SOX2+ cancer cell population." (PMID 37310654, 2023). "The nuclear-enriched abundant transcript 1 (NEAT1) is a lncRNA overexpressed in many human cancer types, and its enhanced expression is associated with a worse prognosis in cancer patients." (PMID 37143733, 2023). "Consistent with a recent study in cancer research, here we found that miR-128-3p is a functional target of Neat1 in pathogenic Th17 cells." (PMID 37716986, 2023).
cancer (continued). "NEAT1 has been also associated with diseases such as cancer, immune inflammation, and neurodegeneration." (PMID 38137449, 2023). "Based on ExInAtor2 analysis, NEAT1 mutations, spanning the entire gene length, display evidence for positive selection in altogether 4 and 3 cancer cohorts in PCAWG and HMF datasets, respectively." (PMID 37291246, 2023). "The recent knowledge exhibits an overview by which NEAT1 and paraspeckles are associated with cancer." (PMID 37310654, 2023). "NEAT1 overexpression was linked to carcinogenesis and cancer development, and NEAT1 has been described as an oncogenic gene in several malignancies." (PMID 37143570, 2023). "H19 and NEAT1 are also reported to be associated with the resistance of cancer cells to chemotherapeutic drugs including bortezomib and dexamethasone respectively." (PMID 36899924, 2023). "Based on our transcriptome analysis after ALYREF knock-down, several RNAs including the short isoform of the cancer-associated noncoding RNA NEAT1, were positively correlated (down-regulated) in the three tested TNBC cell lines." (PMID 35776213, 2022). "Further studies are required to determine the exact mechanism of NEAT1 involved in carcinogenesis and the underlying mechanism of NEAT1 dysregulation in human cancers." (PMID 35676702, 2022). "LncRNA Neat1 plays an indispensable role in promoting cancer in a variety of tumors and produces two splicing variants: Neat1_1 and Neat1_2." (PMID 36335386, 2022). "Another study showed that NEAT1 expression is increased in exosomes derived from cancer-associated fibroblasts (CAFs) compared with exosomes derived from normal fibroblasts." (PMID 36011001, 2022). "Although the NEAT1-miR-23a-3p association has been reported in other cancers, our data provide a first insight into the roles of NEAT1-miR-23a-3p-GLS axis in cisplatin sensitivity of MB cells." (PMID 35313796, 2022). "It has been shown that the expression of NEAT1 is regulated in both cancer and para-cancerous states and that targeting NEAT1 causes a strong inhibition of tumour growth, accelerating the apoptotic process of CRC." (PMID 35457155, 2022). "Studies have shown that NEAT1 plays regulatory roles in various cancers, and high expression of NEAT1 is strongly associated with poor prognosis." (PMID 34231706, 2021). "To date, dozens of studies have reported an association between NEAT1 and resistance to chemotherapy or radiotherapy in various cancers." (PMID 34512157, 2021). "Studies have demonstrated the dysregulation of NEAT1 expression during the progression of cancer, where its expression is considerably linked to tumor size, distant metastasis, TNM stage, drug resistance, and patient survival." (PMID 34885213, 2021). "The potential of NEAT1 as a possible diagnostic marker has been proposed in several cancers, such as prostate and breast." (PMID 34680193, 2021). "For example, NEAT1 is implicated in tumor recurrence and chemotherapy resistance via inducing cancer stem cells (CSC)-like properties in non-small cell lung cancer (NSCLC) cells." (PMID 33292252, 2020). "Altogether, NEAT1 is an excellent example of a cancer-associated lncRNA, which is collectively regulated by multiple RBPs that can either enhance its stability (HuR and SRSF1) or promote its degradation (AUF1 and PABPN1)." (PMID 32340118, 2020). "Some SE‐associated ce‐lncRNAs with high degree/betweenness were highly associated with cancer hallmarks, including lncRNAs reported in cancer (e.g., NEAT1, HOTAIR, XIST, and SNHG5)." (PMID 32460441, 2020). "In another recent study, including information from transposon-mutagenesis screens, however, NEAT1 was identified as one out of eight lncRNAs with cancer driver mutations." (PMID 33329688, 2020).
cancer (continued). "Dysregulation of NEAT1 is associated with tumor growth, recurrence, metastasis and patient survival in numerous cancers." (PMID 33298086, 2020). "Taken together, the well-studied RNA component of nuclear speckles, NEAT1, is recurrently mutated and subjected to SCNAs, causally implicated in cancer." (PMID 33329688, 2020). "The well‐established lncRNA NEAT1, a SE‐associated ce‐lncRNAs, was also top ranked in terms of expression level, the topological degree and cancer hallmark enrichment." (PMID 32460441, 2020). "Dysregulated NEAT1 expression has been documented in a large panel of human cancers, and is associated with poor overall survival in these cancers." (PMID 32843056, 2020). "We identified for the first time that NEAT1 is associated with chemoresistance and cancer stem cell property in TNBC." (PMID 30894512, 2019). "Several studies have shown that aberrant expression of Neat1 is associated with various types of cancer, and its overexpression correlates with poor prognosis." (PMID 31673072, 2019). "In some cancers, the upregulation of NEAT1 and associated paraspeckles can be driven by tumor microenvironmental conditions and estrogen receptor stimulation, respectively." (PMID 31921848, 2019). "High levels of NEAT1 have been shown to be associated with advanced tumor stage and cancer progression, the occurrence of metastasis, and poor patient survival." (PMID 30430751, 2019). "Paraspeckles and NEAT1 have also been linked to cancer biology, where they can have both oncogenic and tumor suppressive roles." (PMID 31921848, 2019). "NEAT1 is frequently overexpressed in cancer tissues, including ccRCC, where it is linked to EMT and chemoresistance by competing with miR-34a and thus, influencing the miR-34a/c Met axis." (PMID 31627266, 2019). "In all these different cancer types, upregulation of NEAT1 is associated with tumor stage and progression, metastasis, and an unfavorable patient survival." (PMID 30430751, 2019). "NEAT1 is up-regulated in various types of cancers and has been reported to be associated with unfavorable prognosis in cancer patients." (PMID 29764424, 2018). "A recent study demonstrated that high NEAT1 expression was associated with a poor prognosis in cancer patients." (PMID 29556074, 2018). "The chemotherapy resistance is the critical cause for cancer-related deaths in OS, thus we investigated the impacts of the oncogene NEAT1 on cisplatin (DDP)-based chemotherapy." (PMID 29654165, 2018). "High NEAT1 expression in cancerous tissues was reported to be associated with prognosis and overall survival (OS) in several cancers." (PMID 28507281, 2017). "This meta-analysis is the first to evaluate the association between NEAT1 levels and cancer prognosis." (PMID 28507281, 2017). "The results indicated that high NEAT1 expression was significantly associated with shorter OS times in cancer patients." (PMID 28507281, 2017). "NEAT1 has been shown to be hypermutated in other cancers and some studies also linked high NEAT1 association with unfavorable prognosis." (PMID 28358873, 2017). "The NEAT1 exon region experiences an elevated mutation rate across cancers, when compared to its flanking background regions." (PMID 28128360, 2017). "Recent studies have demonstrated that the lncRNA, nuclear paraspeckle assembly transcript 1 (NEAT1), was aberrantly up-regulated in various types of cancers and was reported to be associated with unfavorable prognosis in cancer patients." (PMID 27926523, 2017). "This meta-analysis was conducted to assess the association between NEAT1 levels and survival times of cancer patients." (PMID 28507281, 2017). "In the present study, the meta-analysis results implied that high NEAT1 expression was significantly associated with poor prognosis in patients with different types of cancers." (PMID 27926523, 2017). "NEAT1 expression is required for human mammary gland development and lactation, and is associated with cancer progression." (PMID 28911096, 2017).
cancer (continued). "Recently, the long non-coding RNA (lncRNA) NEAT1 has been identified as an oncogenic gene in multiple cancer types and elevated expression of NEAT1 was tightly linked to tumorigenesis and cancer progression." (PMID 27351135, 2016). "Correlation analysis reveals significant association between NEAT1 and cell cycle in cancer cells." (PMID 39085744, 2025). "The exocrine NEAT1, originating from cancer‐associated fibroblasts, can be transferred to EC cells." (PMID 40070309, 2025). "Additionally, the association of high NEAT1 expression with more aggressive cancer characteristics indicates a potential need for more tailored and possibly intensive treatment approaches for patients exhibiting high NEAT1 levels." (PMID 39139172, 2024). "The Multi-3D (scRNA-seq & stRNA-seq) tool enables the examination of the complex interplay between NEAT1-associated ceRNA networks and functions (such as GO terms, biological pathways, cancer hallmarks, etc.)that influence individual disease pathology and cell fate." (PMID 39470723, 2024). "Here we speculate that the cancer-associated lncRNAs NEAT1 and MALAT1 may modulate A3B activity, possibly by sequestration or serving as suicide substrates." (PMID 39322638, 2024). "In order to provide a more global perspective of the ceRNA regulatory relationships associated with NEAT1, the CeCellLand (scRNA-seq & stRNA-seq) tool offers a comprehensive landscape of ceRNA distribution across a range of pan-cancers and normal tissues/organs." (PMID 39470723, 2024). "NEAT1 has been implicated in platinum resistance in various cancers." (PMID 39401197, 2024). "If NEAT1 affects normal shelterin activity, it may cause impaired telomere function and chromosomal imbalances, which are common in cancer cells." (PMID 39578854, 2024). "The high expression of lncRNA NEAT1 may be a risk factor for poor prognosis in patients with malignant tumors, and lncRNA NEAT1 can be used as a potential biomarker to evaluate its prognosis." (PMID 39139172, 2024). "Moreover, overexpression of NEAT1 in cancer tissues has been proven to be associative with increased cell proliferation, migration, and invasion, as well as decreased cell apoptosis, according to a series of studies." (PMID 36980995, 2023). "NEAT1 is associated with cancer initiation, metastasis, recurrence and patient survival." (PMID 37752791, 2023). "NEAT1 knockdown inhibited proliferation and caused G0/G1 cell cycle arrest in cancer cells." (PMID 37310654, 2023). "Another NF-κB-associated lncRNA reported to be upregulated in cancer cells is lncRNA NEAT1." (PMID 36899924, 2023). "Exosomal NEAT1 plays an important role in cancers and may serve as a diagnostic or treatment marker." (PMID 36011001, 2022). "High NEAT1 is positively associated with a worse prognosis and low survival of cancer patients." (PMID 35313796, 2022). "LncRNA NEAT1 is one of the most widely studied lncRNAs associated with a variety of human cancers." (PMID 35300348, 2022). "HyPro labeling identifies dynamic changes in RBPs and transcripts associated with NEAT1 and, thus, may be a powerful approach to assess the function of paraspeckles in the context of diseases such as cancer." (PMID 35457249, 2022). "Is the metabolism of NEAT1 transcripts druggable and could it potentially be exploited to interfere with cancer-associated NEAT1 functions?" (PMID 35457249, 2022). "The integration of the differentially expressed ncRNAs, with an exhaustive computational analysis of their experimentally supported targets, led us to dissect complex networks integrated by the cancer-related lncRNAs Malat1, Neat1, H19, Meg3, and their associated miRNA-target pairs." (PMID 34222014, 2021). "Well‐renowned lncRNAs, such as NEAT1, widely implicated in numerous cancers, can also have a function in adipogenesis, and indeed NEAT1 has been found to modulate the splicing of PPARγ, increasing the expression of the isoform 2 through SRp40 association in 3T3‐L1 pre‐adipocyte." (PMID 33443301, 2021).
cancer (continued). "Furthermore, lncRNAs with cancer-associated SNPs, such as NEAT1, Gas5, or ANRIL have been linked to inflammation." (PMID 33329688, 2020). "Moreover, the involvement of lncRNA H19 and NEAT1 in HDAC activity has been reported in association with cancer." (PMID 33050646, 2020). "In a pan-cancer study, an enrichment of indel mutations in the NEAT1 locus was observed." (PMID 33329688, 2020). "The expression level of NEAT1 is associated with clinicopathological features of cancer patients." (PMID 32296457, 2020). "The higher expression of NEAT1 is significantly associated with worse survival in cancer patients." (PMID 33308223, 2020). "Multiple recent reports suggest a causal link between NEAT1 gene aberrations and cancer." (PMID 33329688, 2020). "Second, since the advent of immune evasion is closely associated with cancer development and growth, NEAT1 may have oncogenic properties and induce tumor growth." (PMID 31850199, 2019). "Strikingly, some studies revealed that NEAT1 could be detected in the circulation and was dysregulated in peripheral blood mononuclear cells in several cancers; these suggested that NEAT1 is a potential diagnostic and prognostic biomarker in cancers." (PMID 30894512, 2019). "In this review, we highlight the latest insights into the expression pattern, biological roles and mechanisms underlying the function and regulation of NEAT1 in tumors, and especially focus on its clinical implication as a new diagnostic biomarker and an attractive therapeutic target for cancers." (PMID 30374364, 2018). "However, the detailed mechanisms of why NEAT1 was associated with oncologic outcome in cancer were unclear." (PMID 28507281, 2017). "NEAT1 has been previously associated with the growth of several cancers." (PMID 28968960, 2017). "In this regard, NEAT1 has been suggest as a potential diagnostic marker and may represent a novel target for the treatment of cancers." (PMID 27926523, 2017). "High NEAT1 expression is associated with a poor prognosis in cancer patients." (PMID 28507281, 2017). "A lot of efforts have been made to understand the functional role of NEAT1 in cancer progression, but the underlying molecular mechanisms of NEAT1 involved cancer progression are largely unknown." (PMID 27926523, 2017). "However, to reinforce the findings, better standardized methods with large sample sizes are needed to further confirm the association between NEAT1 and clinical outcomes of cancers in various ethnic populations." (PMID 28507281, 2017). "The meta-analysis results from present study suggested that increased expression level of NEAT1 was associated with unfavorable prognosis and may serve as a predictive factor for clinicopathological features in various cancers." (PMID 27926523, 2017). "In all, our results indicated that high NEAT1 expression may be a risk factor for shorter OS and a useful biomarker to predict poorer prognosis in human cancers." (PMID 28507281, 2017). "Results of the analysis showed that NEAT1 expression in human cancer was significantly associated with OS (hazard ratio [HR]=1.53, 95% confidence interval [CI]: 1.39–1.68), including digestive system tumor (HR=1.54, 95% CI: 1.37–1.73) and respiratory carcinomas (HR=1.44, 95% CI: 1.11–1.85)." (PMID 28507281, 2017). "Several studies indicated NEAT1 is associated with various cancers." (PMID 28358873, 2017). "Differential expression of NEAT1 variants may be potentially relevant in other cancer types; therefore, further studies in patients with other cancer types are also needed." (PMID 26552600, 2015). "Additionally, information is provided on whether NEAT1 and its downstream targets have been validated in experiments as cancer biomarkers associated with cancer cell growth, metastasis, disease recurrence, survival, drug resistance, and immune escape." (PMID 41099605, 2026).